DUSP5 (dual specificity phosphatase 5)
Diseases named in the same sentence as DUSP5 in open-access papers (continued):
Sharing a sentence is not in itself a finding about the gene and the disease.
papilloma (5 papers, 2016 to 2025). A benign epithelial neoplasm that projects above the surrounding epithelial surface and consists of villous or arborescent outgrowths of fibrovascular stroma. "Another paper, supporting the antiproliferative role of DUSP5, showed that DUSP5 KO mice show increased sensitivity to HRas (HRasQ61L)-driven papilloma formation in the 7,12-dimethylbenz[a]anthracene/12-O-tetradecanoylphorbol-13-acetate (DMBA/TPA) model of skin carcinogenesis." (PMID 40943262, 2025). "Loss of DUSP5 did not influence the mechanism of carcinogenesis as 90% of the DUSP5−/− papillomas contained the signature HrasQ61L mutation, nor was tumour morphology or size affected by DUSP5 deletion." (PMID 26791049, 2016). "In vivo, mice lacking DUSP5 show a greatly increased sensitivity to mutant Ras-driven papilloma formation in a pharmacological model of induced skin carcinogenesis." (PMID 28910386, 2017). "Lack of DUSP5 in mouse embryo fibroblasts leads to increase nuclear phospho ERKs content, and lack of DUSP5 in mouse increases sensitivity to mutant Harvey-Ras (HRasQ61L)-driven papilloma." (PMID 27376062, 2016). "In a skin carcinogenesis mouse model, papilloma formation was found in mice lacking DUSP5 and its regulation of nuclear ERK activity also served DUSP5 as tumor suppressor in epidermis Ras modulation." (PMID 35368866, 2022).
viral infection (5 papers, 2016 to 2023). "However, loss of DUSP5 affects memory/effector CD8+ T cell populations in response to acute viral infection." (PMID 27936095, 2016). "The results demonstrate that E. coioides DUSP5 could inhibit SGIV infection by regulating E. coioides immune-related factors, indicating that DUSP5 might be involved in viral infection." (PMID 37766214, 2023). "However, the role of DUSP5 in viral infection of teleosts remains need further study." (PMID 37766214, 2023).
Cerebral ischemia (4 papers, 2017 to 2024). Restriction of arterial blood supply to the brain associated with insufficient oxygenation to support the metabolic requirements of the tissue. "For example, LncRNA H19 induces autophagic cell death in cerebral ischemia and reperfusion (I/R) injury by inhibiting DUSP5 to phosphorylate ERK1/2 and provoke autophagy." (PMID 34759263, 2021). "LncRNA H19 activates autophagy by inhibiting DUSP5, which diminishes the inhibitory effect of DUSP5 on ERK1/2, induces cerebral ischemia reperfusion injury." (PMID 38799506, 2024). "As for the EPO inducing effect on PTPRE, it is interesting to note that another phosphatase, dual-specificity protein phosphatase 5 (Dusp5), was among the few genes induced by EPO in rats with cerebral ischemia, where EPO treatment is protective." (PMID 29123527, 2017).
cervical cancer (4 papers, 2017 to 2024). A primary or metastatic malignant neoplasm involving the cervix. "The suppression of DUSP5 through EZH2-mediated methylation further enhances cervical cancer cell proliferation and migration." (PMID 39090630, 2024). "DUSP5, which is expressed at very low levels in cervical cancer cells, has been verified to be negatively modulated by lncRNA ARAP1 antisense RNA 1 and to contribute to cell proliferation and migration." (PMID 35368866, 2022). "So far, the impact of DUSP5 inactivation in tumorigenesis has only been studied in vitro in human gastric and uterine cervix cancer cells and was responsible respectively for enhanced cell proliferation or massive apoptosis." (PMID 28910386, 2017). "Given its demonstrated inverse correlation with clinical cancerous tissues, DUSP5 may serve as a potential therapeutic target for cervical cancer." (PMID 35368866, 2022). "Our current study showed that expression of DUSP5 is severely repressed in cervical cancer tissues." (PMID 35368866, 2022). "In the context of cervical cancer, ARAP1-AS1 recruits EZH2 to the DUSP5 promoter, resulting in epigenetic silencing of DUSP5." (PMID 39090630, 2024). "In the previous study, ARAP1-AS1 was discovered to recruit EZH2 to regulate the expression of dual specificity phosphatase 5, a downstream gene of ARAP1-AS1, therefore affecting the development of cervical cancer." (PMID 35291911, 2022). "While HPV16 E7-negative cervicitis tissues showed high DUSP5 levels, HPV16 E7-positive cervical intraepithelial neoplasia (CIN) and cervical cancer tissues showed low DUSP5 expression levels, indicating that DUSP5 plays an important role in disease progression." (PMID 35368866, 2022). "Indeed, gene expression levels of DUSP5 were significantly lower in HPV16 single positive cervical cancer tissues compared with normal cervical control tissues, indicating a possible inverse correlation between HPV16 E7 and DUSP5." (PMID 35368866, 2022).
colon cancer (4 papers, 2015 to 2023). "ROR-AS1/EZH2 inhibits the apoptosis of colon cancer by facilitating H3K27me3 on the DUSP5 promoter." (PMID 33050646, 2020). "In colon cancer, lncRNA ROR1-AS1 can also bind to EZH2 and downregulate the expression of DUSP5." (PMID 33050646, 2020).
glioblastoma (4 papers, 2015 to 2025). The most malignant astrocytic tumor (WHO grade IV). "The expressions of DUSP1, DUSP5, and DUSP6 were predominantly reported in pseudopalisading and perinecrotic regions of the GBM aggressive tumor, as reported in the Ivy Glioblastoma (GBM) Atlas Project (Ivy GAP) repository." (PMID 41158869, 2025).
Hypertension (4 papers, 2015 to 2023). The presence of chronic increased pressure in the systemic arterial system. "It is plausible that the KO of Dusp5 may also mitigate macrophage infiltration, as we observed in the kidney following hypertension induction in this model." (PMID 37588944, 2023). "In the kidney, Dusp5 KO has been shown to protect against hypertension-induced impaired renal hemodynamics, attenuate elevated glomerular capillary permeability, renal fibrosis, medullary protein cast formation, macrophage infiltration, and epithelial-mesenchymal transformation." (PMID 37588944, 2023). "In the kidney, hypertension‐related renal damage was significantly attenuated in Dusp5 KO rats." (PMID 31960618, 2020). "In the kidney, improved hemodynamics in Dusp5 KO rats may contribute, at least in part, to the protection from hypertension‐related renal damage." (PMID 31960618, 2020).
osteoarthritis (4 papers, 2020 to 2025). A noninflammatory degenerative joint disease occurring chiefly in older persons, characterized by degeneration of the articular cartilage, hypertrophy of bone at the margins and changes in the synovial membrane. "In this study, we identified and validated four differentially expressed genes (CXCL8, CXCL2, DUSP5, and TNFSF11) as promising diagnostic biomarkers for osteoarthritis (OA), which collectively mediate immune regulation, inflammatory responses, and bone remodeling in OA pathogenesis." (PMID 40672822, 2025). "Knockdown of DUSP5 can inhibit IL-1β-induced expression of inflammatory genes and activation of NF-κB and ERK signaling pathways, increasing the incidence of osteoarthritis." (PMID 37766214, 2023).
skin cancer (4 papers, 2016 to 2022). "Of interest, DUSP5 knock-out mice treated with the DMBA/TPA-inducible skin carcinogenesis protocol in order to acquire Hras mutations driving skin papilloma development experienced twice as many skin cancers as DUSP5 wild-type mice." (PMID 34360545, 2021). "Mice lacking DUSP5 developed twice as many skin tumours when compared with wild type animals, while mice lacking one copy of DUSP5 showed an intermediate phenotype." (PMID 26791049, 2016). "Thus we conclude that in contrast to results obtained in the HRASQ61L-driven murine skin cancer model, SERPINB2 is not a mediator of the effects of DUSP5 loss in the pancreas." (PMID 35418690, 2022).
autoimmune disease (3 papers, 2019 to 2024). A disorder resulting from loss of function or tissue destruction of an organ or multiple organs, arising from humoral or cellular immune responses of the individual to their own tissue constituents. "The literature has shown the critical role that DUSP5 plays in disorders that include vascular disease, cancer, autoimmune disease and substance use disorder." (PMID 39749114, 2024). "Specifically, DUSP5’s role in substance use disorder, cancer, autoimmune diseases and vascular development." (PMID 39749114, 2024). "Nevertheless, the inhibition of DUSP1 and overexpression of DUSP5 may be potential therapeutic approaches for autoimmune diseases, including SLE." (PMID 31766293, 2019). "In addition, DUSPs are also involved in either human autoimmune diseases (DUSP2, DUSP7, DUSP10, and DUSP12) or T-cell activation (DUSP1, DUSP5, and DUSP14)." (PMID 31766293, 2019).
esophageal cancer (3 papers, 2016 to 2024). A primary or metastatic malignant neoplasm involving the esophagus. "DUSP5 was the most epimutated DUSP in Stomach (17%), Pancreas (2%) and equal to DUSP26 in Oesophageal cancer (9%)." (PMID 38475971, 2024).
neuroblastoma (3 papers, 2014 to 2024). Neuroblastoma (NB) is the most common solid, extracranial childhood tumor. "Cells from other tumor types (Burkitt's lymphoma, leukemia, neuroblastoma, Ewing sarcoma) also showed a higher DUSP5P1/DUSP5 ratio than normal cells." (PMID 24651368, 2014).
pancreatic cancer (3 papers, 2015 to 2022). "Despite reports of SERPINB2 expression in human pancreatic cancers, RT-qPCR analysis of wild type and Dusp5−/− pancreata revealed very low levels of pancreatic SerpinB2 mRNA expression compared with levels seen in skin." (PMID 35418690, 2022). "Here we use deletion of either Dusp5 or Dusp6 to explore the roles of these phosphatases in a murine model of KRASG12D-driven pancreatic cancer." (PMID 35418690, 2022). "We therefore obtained a second conditional strain (Dusp5Mfl/fl), which expresses wild type levels of DUSP5 protein and is efficiently deleted by Cre recombinase in both MEF’s and mouse tissue and repeated our pancreatic cancer experiments aging mice to 56 and 100-days." (PMID 35418690, 2022). "Finally, our data suggests that Cav-1 depletion in pancreatic cancer cells affects various pathways, particularly the JAK/STAT pathway, by decreasing activation of JAK2 and STAT3 and by increasing SOCS2, PIAS3, and DUSP5 inhibitory signals." (PMID 26065715, 2015). "Our data demonstrate that both DUSP5 and DUSP6 perform at least partially non-redundant functions in restraining the early stages of murine pancreatic cancer development driven by oncogenic mutant KRASG12D." (PMID 35418690, 2022).
pulmonary hypertension (3 papers, 2021 to 2023). Increased pressure within the pulmonary circulation due to lung or heart disorder. "Dual-specificity protein phosphatase 5 (DUSP5) has been implicated in several pathological conditions, including pulmonary hypertension and cancer, but its role in AD/ADRD remains unclear." (PMID 37588944, 2023). "Interestingly, DUSP5 expression has been shown to be upregulated by angiotensin II (ANG II) in primary rat aortic VSMCs, but DUSP5 serves as a negative regulator of ANG-II-mediated cell proliferation in VSMCs from de-identified patients with pulmonary arterial hypertension." (PMID 37588944, 2023). "In response to angiotensin II infusion, mice lacking DUSP5 develop pulmonary hypertension and right ventricular cardiac hypertrophy." (PMID 34142888, 2021). "In addition, it has been shown that DUSP5-mediated ERK suppression can serve as a protective mechanism by blocking pulmonary vascular smooth muscle cell proliferation, by preventing pulmonary hypertension and right ventricular cardiac hypertrophy and by inhibiting inflammation in adipocytes." (PMID 35368866, 2022).
Sepsis (3 papers, 2016 to 2023). Sepsis is defined as life-threatening organ dysfunction caused by a dysregulated host response to infection. "One study identified SLC2A6, C1ORF55, DUSP5 and ROHB as key genes in sepsis (AUC>0.75) by the LASSO method, while SLC2A6 is thought to be positively associated with the level of infiltration of Th1 cells." (PMID 37456759, 2023).
adenoma (2 papers, 2018 to 2019). A neoplasm arising from the epithelium. "Similarly, DUSP5 overexpression had no impact on tumour size or the pattern and intensity of pERK staining in the adenomas." (PMID 29379130, 2018). "Furthermore, transgenic overexpression of DUSP5 in the mouse intestinal epithelium did not alter basal p-ERK levels or ERK-regulated gene expression, cell differentiation, proliferation or adenoma formation, processes that require activation of this pathway." (PMID 29379130, 2018). "Furthermore, a transgenic mouse overexpressing DUSP5 in the intestinal epithelium displayed no alterations in ERK signalling, intestinal homeostasis or adenoma formation and the authors concluded that DUSP5 does not regulate intestinal development or tumourigenesis." (PMID 30401534, 2019).
atherosclerosis (2 papers, 2022 to 2025). A disease characterized by the build-up of fatty material and calcium deposition in the arterial wall resulting in partial or complete occlusion of the arterial lumen. "MiR-23a-3p could promote endothelial inflammation by targeting Dusp5 and maintaining ERK1/2 phosphorylation, which may transfer atherosclerosis to remote locations." (PMID 41296393, 2025).
Autoimmunity (2 papers, 2014 to 2019). The occurrence of an immune reaction against the organism's own cells or tissues. "Over-expression of DUSP5 in transgenic mice results in autoimmunity but also in reduced T-cell proliferation." (PMID 24651368, 2014). "Further investigation will be needed to clarify the role of DUSP5 in autoimmunity." (PMID 31297117, 2019).
bladder cancer (2 papers, 2016 to 2025). "Compound 27 inhibited bladder cancer progression by upregulating DUSP5 expression and negatively regulating the p38 MAPK pathway, modulating the immune response and promoting apoptosis." (PMID 40473811, 2025). "Compound 27 effectively modulates the p38 MAPK signaling pathway by stably binding to DUSP5 and promotes cell apoptosis by upregulating the expression level of DUSP5, thereby inhibiting the occurrence and development of bladder cancer." (PMID 40473811, 2025). "Therefore, compound 27 effectively negatively regulates the p38 MAPK signaling pathway by stably binding to DUSP5 and promotes apoptosis by upregulating the expression levels of DUSP5, thereby inhibiting the occurrence and development of bladder cancer." (PMID 40473811, 2025).
COVID-19 (2 papers, 2021 to 2022). A disease caused by infection with severe acute respiratory syndrome coronavirus 2. "To confirm this observation, we analyzed the expression of DUSP1 and DUSP5 in nasopharyngeal swabs from severe COVID-19 patients recruited from a local hospital." (PMID 33995033, 2021). "Given that the SARS-CoV-2 infection does increase the pro-inflammatory cytokines level, the combined effect of these medications on DUSP1 and DUSP5 expression might play a significant role in attenuating the immunopathology of COVID-19." (PMID 33995033, 2021). "It is possible that theophylline administration to COVID-19 patients increases the expression of DUSP1 and DUSP5 to such an extent that they contribute to the treatment of the illness." (PMID 35456985, 2022). "Moreover, in COVID-19 patients, high levels of DUSP1 and DUSP5 have been detected, especially in severe cases." (PMID 35456985, 2022). "Among medications used for COVID-19, chloroquine increased both DUSP1 and DUSP5 expressions." (PMID 33995033, 2021). "Identifying elements contributing to the dysregulation of these pro-inflammatory cytokines during COVID-19, such as reduced expression of DUSP1 and DUSP5, may pave the way for therapeutic intervention to control the level of these cytokines and hence their pathological implications." (PMID 33995033, 2021).
cystic teratoma (2 papers, 2022 to 2024). "From our previous report, DUSP5 and PHLDA1 mutations in mature cystic teratomas of the ovary identified on whole‐exome sequencing may explain teratoma characteristics in terms of osteogenic differentiation and hair growth." (PMID 38907278, 2024).
diabetic cardiomyopathy (2 papers, 2021 to 2023). Diabetic cardiomyopathy is a disorder of the heart muscle in people with diabetes. "In diabetic patients, HDAC3 is activated and inhibits Dusp5 expression by deacetylating histone H3 on the primer region of the Dusp5 gene, which in turn leads to ERK1/2 activation and the development of diabetic cardiomyopathy (DCM)." (PMID 37175583, 2023).
heart failure (2 papers, 2021 to 2025). Inability of the heart to pump blood at an adequate rate to meet tissue metabolic requirements. "Here, we sought to determine if a brief course of combined DUSP5 suppression plus T3 therapy replaces cardiomyocytes lost due to preexisting doxorubicin injury and reverses heart failure." (PMID 33754028, 2021). "MR analysis identified significant causal associations between the genes implicated in BW loss (ADD3, HSPA12A, SLC18A2, PDZD8, DUSP5, CASP7) as well as EF% and LV volumes (GPC6, UGGT2, SLAIN1, POU4F1, MBNL2) in BXD mice post-DOX and heart failure (HF) outcomes in humans." (PMID 40321772, 2025).
hemangioma (2 papers, 2015 to 2017). A benign vascular lesion characterized by the formation of capillary-sized or cavernous vascular channels. "However, if inhibiting DUSP5 accelerates the disease in the first phase as the putative tumor suppressor role of DUSP5 would suggest, then, perhaps the involution second phase of hemangiomas could be triggered earlier assuming that the two phases are linked by a common mechanism involving DUSP5." (PMID 26286528, 2015).
Lewis lung carcinoma (2 papers, 2017 to 2021). "Conditioned medium from LLC (Lewis lung carcinoma) cells can increase Runx2/VEGF/Dusp5 expressions in mast cells, and promote tumor angiogenesis." (PMID 34135893, 2021). "Conditioned medium from LLC (Lewis lung carcinoma) cells increase the expression of cell surface receptors and a pro-angiogenic Runx2/VEGF/Dusp5 axis in mast cells, which promotes tumor angiogenesis." (PMID 28968979, 2017).
Myocardial fibrosis (2 papers, 2021 to 2023). "Although there was a trend to a reduction in myocardial fibrosis with DUSP5 siRNA+T3 treatment, this failed to reach statistical significance." (PMID 33754028, 2021).
papillary thyroid carcinomas (2 papers, 2017 to 2024). "DUSP5 mRNA levels were 7.9 fold higher in BRAF-mutated papillary thyroid carcinoma (PTC) than in normal adjacent tissue (P = 6.3.10−58) and 1.5 fold higher in RAS-mutated PTC than in normal adjacent tissue (P = 8.10−3)." (PMID 28910386, 2017). "DUSP5 is overexpressed in human papillary thyroid carcinomas (PTCs), and DUSP5 silencing suppresses the migratory ability and invasiveness of PTCs cells." (PMID 38872157, 2024).
psoriasis (2 papers, 2020 to 2022). An autoimmune condition characterized by red, well-delineated plaques with silvery scales that are usually on the extensor surfaces and scalp. "In keratinocytes, previous studies have shown that the expression of DUSP2 and DUSP5 changed in response to an adalimumab treatment in psoriasis patients whereas arsenic, a human carcinogen that can cause squamous cell carcinomas (SCCs), could inhibit the expression of DUSP2 or DUSP14." (PMID 36080217, 2022).